HEG1 (heart development protein with EGF like domains 1)
Description:
Receptor component of the CCM signaling pathway which is a crucial regulator of heart and vessel formation and integrity. May act through the stabilization of endothelial cell junctions.
Synonyms: KIAA1237; HEG; MST112; MSTP112
Tractability: Small molecule: a structure with a bound ligand is known. Antibody: UniProt places it where antibodies can reach, with high confidence; UniProt predicts a signal peptide or a membrane-spanning region; its Gene Ontology location is reachable by antibodies, with medium confidence; the Human Protein Atlas places it where antibodies can reach. PROTAC: ubiquitination databases record sites on it; its protein half-life has been measured.
Gene: Protein-coding gene on chromosome 3 (124,965,710 to 125,055,997, reverse strand). Ensembl gene ENSG00000173706.
Subcellular location: Cell membrane (Isoform 1); Cell junction; Secreted (Isoform 2)
Subcellular location (Human Protein Atlas): Vesicles; Plasma membrane
Gene Ontology:
Molecular function: protein binding; calcium ion binding
Biological process: negative regulation of membrane permeability; negative regulation of Rho protein signal transduction; protein localization to cell junction; heart development
Cellular component: cell-cell junction; anchoring junction; extracellular region; plasma membrane
Genetic constraint (gnomAD): Loss-of-function variants: 53 observed, 103.28 expected, observed/expected ratio (o/e) 0.51, 90% interval 0.41 to 0.64. The upper end of that interval is the gene's LOEUF score, 0.64, which puts it in group 2 of 6, group 1 being the genes least tolerant of losing a copy. Missense variants: 1,416 observed, 1,552.8 expected, observed/expected ratio (o/e) 0.91, 90% interval 0.87 to 0.95. Synonymous variants: 593 observed, 612.23 expected, observed/expected ratio (o/e) 0.97, 90% interval 0.9 to 1.04.
Homologues: Orthologues: chimpanzee HEG1 (99% identical), macaque HEG1 (93% identical), rabbit HEG1 (65% identical), dog HEG1 (63% identical), mouse Heg1 (61% identical), rat Heg1 (60% identical), guinea pig HEG1 (60% identical), pig HEG1 (58% identical), zebrafish heg1 (23% identical).
Diseases named in the same sentence as HEG1 in open-access papers:
HEG1 is named in the same sentence as 48 diseases in open-access papers, as found by Europe PMC text mining. Sharing a sentence is not in itself a finding about the gene and the disease. The quoted sentences say what the papers report.
mesothelioma (11 papers, 2017 to 2026). A usually malignant and aggressive neoplasm of the mesothelium which is often associated with exposure to asbestos. "Recently, HEG1 was observed to be increased and promoting cell proliferation in mesothelioma, HEG1 was considered as a diagnostic biomarker for malignant mesothelioma with specificity and sensitivity reaching 99% and 92%, respectively." (PMID 35950222, 2022). "HEG1 is expressed on apical cell surfaces and is associated with mesothelioma cell proliferation." (PMID 30250045, 2018). "HEG1 expression was found in 43/44 (98%) mesothelioma effusions and 39/42 (93%) surgical mesothelioma specimens, as well as all multicystic and papillary mesothelial tumors." (PMID 41656400, 2026). "In this family, sialylated protein HEG homolog 1 (HEG1) is a novel mesothelial-related biomarker, and its expression supports the survival and proliferation of mesothelioma cells." (PMID 39941848, 2025). "As a result, we believed that HEG1 is incapable of differentiating between mesothelioma and RMC instances." (PMID 40091315, 2025). "Sialylated HEG1 is prominently expressed in many mesothelioma cases, demonstrating its potential as a valuable marker for the differential diagnosis of mesothelioma due to its high specificity." (PMID 37835810, 2023). "The results of neuraminidase treatments of HEG1 or the epitope-fused protein on mesothelioma cells were also similar to those obtained from HEK293T." (PMID 30250045, 2018). "The specific detection of mesothelioma with SKM9-2 can thus be performed by the recognition of sialylated glycan modification in the specific region of HEG1." (PMID 30250045, 2018). "Human HEG1 on mesothelioma cells is a 400 kDa mucin-like membrane protein with a heavily O-glycosylated Ser/Thr rich region that accounts for ~70% of the molecule, but does not contain tandem repeat sequences." (PMID 30250045, 2018). "Sialylated HEG1 was expressed on proliferative cells such as reactive mesothelial cells, endothelial cells in angiogenesis, and mesothelioma." (PMID 28361969, 2017). "Churg and Naso have recently hypothesized that the use of only two immunostains usually could enable the highly accurate differentiation between epithelioid/biphasic mesotheliomas from NSCLC carcinomas using HEG1 and Claudin-4 IHC labelling in combination." (PMID 40091315, 2025). "Moreover, knockdown of the HEG1 gene dramatically decreased the survival and proliferation of mesothelioma cells." (PMID 31262974, 2019). "HEG1 is a 400 kDa mucin-like membrane protein found on mesothelioma." (PMID 30250045, 2018). "Nevertheless, we think that the major glycan in the epitope of mesothelioma HEG1 would be disialyl T, since SKMepmin3 produced from mesothelioma cells showed similar characteristics to the purified SKMepmin3 containing disialyl T with respect to surface charge properties." (PMID 30250045, 2018). "The anti-mesothelioma mAb SKM9-2 recognizes the sialylated protein HEG homolog 1 (HEG1)." (PMID 30250045, 2018). "Further elongation of the glycan at Thr903 could potentially interfere with the approach of SKM9-2 to the epitope in HEG1 and may influence the detection of mesothelioma with SKM9-2." (PMID 30250045, 2018). "It was difficult to identify the sialylated O-linked glycan in the epitope of native HEG1 on mesothelioma cells because the epitope peptides of endopeptidase-digested native HEG1 were not be obtained." (PMID 30250045, 2018). "In light of the association between HEG1 and mesothelioma proliferation, the mAb SKM9-2 and HEG1 may be productive diagnostic tools and therapeutic targets for MM." (PMID 28361969, 2017). "Here we show that sialylated HEG1, which we identified as a novel mucin-like membrane protein, is indeed a mesothelioma-related antigen, and that HEG1 expression supports the survival and proliferation of mesothelioma cells." (PMID 28361969, 2017).
mesothelioma (continued). "We also found that gene silencing of HEG1 significantly suppressed the survival and proliferation of mesothelioma cells; this result suggests that HEG1 may be a worthwhile target for function-inhibition drugs." (PMID 28361969, 2017). "Also, interestingly, the gene HEG1, which codes for a membrane protein that may be targeted in mesothelioma, plays a role in the GO enrichment for cell–cell junction organisation." (PMID 38426634, 2024). "Furthermore, we found that HEG1 on mesothelioma cells contains a unique LacdiNAc structure." (PMID 28361969, 2017). "For mesothelioma as opposed to lung adenocarcinoma, they concluded that membranous HEG1 IHC staining exhibited 100% specificity." (PMID 40091315, 2025). "We have shown in the previous study that the anti-HEG1 mAb SKM9-2 recognizes the glycopeptide sequence and can detect mesothelioma more specifically (99%) and sensitively (92%) than other mAbs against current mesothelioma markers." (PMID 30250045, 2018). "Proliferation of mesothelioma cells was suppressed by HEG1 siRNA, but not control siRNA, in a time-dependent manner." (PMID 28361969, 2017). "Mesothelioma cells disseminated into pleural effusion also expressed sialylated HEG1 on the cell cluster apical surface, but not at cell-cell junctions." (PMID 28361969, 2017). "However, inconsistent to mesothelioma and hepatocellular carcinoma, authors also observed negative staining of HEG1 in all 73 LUAD tissues." (PMID 35950222, 2022). "Therefore, SKM9-2 would recognize the HEG1 peptide sequences (893-SKSPSLVSLPT-903) containing two disialyl T antigens at the positions of Ser893 and Ser900, but not Ser897, in mesothelioma cells as well." (PMID 30250045, 2018).
lung carcinoma (9 papers, 2019 to 2026). "HEG1 was infrequently expressed in breast carcinoma (4/59; 7%), lung carcinoma (2/37; 5%) and cervical/uterine carcinoma effusions (3/29; 10%), but was often detected in tubo-ovarian carcinoma effusions (80/151; 53%) and surgical specimens (99/139, 71%)." (PMID 41656400, 2026). "Four of the five genes (HEG1, PLSCR4, GMFG, and NME4) associated with LC-BC alignments have been observed to be deregulated in lung cancer." (PMID 36101460, 2022). "Taken together, we demonstrate that miR-193b is a new dual-strand tumor suppressing miRNA and their common target genes (i.e., CCND1, AJUBA, and HEG1) are potential targets for the treatment of lung cancer." (PMID 31262974, 2019). "Although we focused on the role of HEG1 as an effector for IGF2BP1 function in OXA resistance, BTBD7 may be also involved in OXA resistance as it has been implicated in chemoresistance in lung Carcinoma A549 Cells54." (PMID 37024475, 2023). "Therefore, it is a challenging problem to clarify the role of HEG1 in lung cancer." (PMID 35950222, 2022). "In the present study, we identified miR-193b-3p and -5p as a new dual-strand tumor suppressor, which inhibits the proliferative and metastatic potential of lung cancer by suppressing common targets, including CCND1, AJUBA, and HEG1." (PMID 31262974, 2019). "It was revealed that miR-193b-3p and -5p regulate malignant phenotypes of lung cancer through the suppression of their common target genes (i.e., CCND1, AJUBA, and HEG1)." (PMID 31262974, 2019). "These included genes such as SCUBE3, MARCKSL1 and PGK1 in lung cancer, SOX4 and GNAS in breast cancer and hepatocellular carcinoma, HEG1 in hepatocellular carcinoma, PLS3 in pancreatic adenocarcinoma, FBN1 and SPARC in gastric cancer and CST1 in gastric cancer and breast cancer." (PMID 40430098, 2025). "HEG1 was not expressed in most lung carcinomas, with only rare cases showing positivity and exhibiting focal membranous or cytoplasmic staining with weak to moderate intensity." (PMID 39941848, 2025). "In the report of lung cancer, because the authors did not provide enough information about the antibody against HEG1, we could not determine the reason for the difference in results compared to the present study." (PMID 37835810, 2023).
malignant mesothelioma (6 papers, 2017 to 2026). A malignant neoplasm of the pleura or peritoneum, arising from mesothelial cells. "The aim of this was study to detect the diagnostic accuracy of the expression of HEG1 and Claudin-4 in distinguishing malignant mesothelioma from lung adenocarcinoma in pleural effusion." (PMID 40091315, 2025). "The aim of this study was to ascertain the diagnostic accuracy (specificity and sensitivity) of HEG1 and Claudin-4 expression in differentiating between lung adenocarcinoma and malignant mesothelioma in pleural effusion cases." (PMID 40091315, 2025). "In addition, recent research has reported that HEG1 is dysregulated in malignant mesothelioma and serves as a stable diagnostic marker for malignant mesothelioma." (PMID 35950222, 2022). "HEG1 had sensitivity of 95% for diagnosing malignant mesothelioma in all studied specimens, with a specificity of 38% in the differential diagnosis from tubo-ovarian carcinoma and 93% in the differential diagnosis from non-tubo-ovarian carcinomas." (PMID 41656400, 2026). "In this study, we compared two scFv linkers, G4S and Whitlow/218, in self-activating SKM-CAR, which recognized a malignant mesothelioma-specific modified HEG1 molecule." (PMID 40308593, 2025). "HEG1, a mucin-like membrane protein is known as a specific marker for malignant mesothelioma." (PMID 31262974, 2019).
hepatocellular carcinoma (5 papers, 2021 to 2025). A malignant tumor that arises from hepatocytes. "Conversely, studies exploring the association between HEG1 protein expression and prognosis remain limited, with the exception of hepatocellular carcinoma (HCC)." (PMID 37835810, 2023). "In hepatocellular carcinoma, HEG1 has been reported to promote the invasion, metastasis, and epithelial‐mesenchymal transition of HCC by activating Wnt/β‐catenin signaling pathway, so it has been considered as a potential prognostic marker and therapeutic target for HCC." (PMID 35950222, 2022).
lung adenocarcinoma (3 papers, 2022 to 2025). A carcinoma that arises from the lung and is characterized by the presence of malignant glandular epithelial cells. "Diagnostic performance of IHC staining for Claudin-4 and HEG1 in diagnosis of lung adenocarcinoma." (PMID 40091315, 2025). "The current study’s HEG-1-stained cell block sections revealed that 96% of MPM cases had positive membranous HEG-1 expression, while only one case of lung adenocarcinoma was positive." (PMID 40091315, 2025). "In 95% of RMCs with benign effusions, cell block sections from this study demonstrated positive membranous HEG-1 immunoexpression; in contrast, just one case of lung adenocarcinoma displayed similar immunoexpression." (PMID 40091315, 2025). "Our study was the first to investigate the expression and clinical significance of HEG1 in lung adenocarcinoma." (PMID 35950222, 2022). "HEG1 is therefore particularly useful in distinguishing lung adenocarcinoma from MPM." (PMID 40091315, 2025). "Comparison between MPM and lung adenocarcinoma regarding IHC staining for Claudin-4 and HEG1." (PMID 40091315, 2025). "HEG1 is therefore particularly useful in distinguishing lung adenocarcinomas from RMCs." (PMID 40091315, 2025). "HEG1 as a novel potential biomarker for the prognosis of lung adenocarcinoma." (PMID 35950222, 2022). "However, the role of HEG1 in lung adenocarcinoma (LUAD) is unclear." (PMID 35950222, 2022). "There was a highly statistically significant difference between HEG1 immunoexpression in MPM and lung adenocarcinoma." (PMID 40091315, 2025). "The relationship of prognosis between HEG1 expression and malignant diseases has been reported in HCC and lung adenocarcinoma." (PMID 37835810, 2023). "Also, positive membranous HEG1 immunoexpression was found in 96% of cases of MPM, and only 2.6% of lung adenocarcinoma cases." (PMID 40091315, 2025). "Additionally, there was a statistically significant variation in the HEG-1 immunoreactivity between MPM and lung adenocarcinoma." (PMID 40091315, 2025). "HEG1 was found to be positive in 24 out of 25 cases (96%) of MPM and negative in 38 out of 39 cases (97.4%) of lung adenocarcinoma." (PMID 40091315, 2025).
Pleural effusion (3 papers, 2017 to 2025). The presence of an excessive amount of fluid in the pleural cavity. "HEG1 and Claudin-4 IHC staining together are particularly useful for differentiating reactive or malignant mesothelial cells from adenocarcinoma in pleural effusion." (PMID 40091315, 2025).
atherosclerosis (2 papers, 2025). A disease characterized by the build-up of fatty material and calcium deposition in the arterial wall resulting in partial or complete occlusion of the arterial lumen. "Recent studies indicate that atheroprotective shear stress induces HEG1-mediated KLF2 and KLF4 expression, and endothelial HEG1 is downregulated in individuals with advanced atherosclerosis." (PMID 40172727, 2025).
cardiomyopathy (2 papers, 2018 to 2021). A disease of the heart muscle or myocardium proper. "As a cardiac development protein associated with cardiomyopathy, HEG1 had been identified as one of the important targets of NXT in the treatment of cardiomyopathy." (PMID 34775978, 2021). "RNA-seq analysis in this study revealed that heg1-ccm signaling was down-regulated in TFD-induced cardiomyopathy zebrafish embryonic hearts." (PMID 34775978, 2021). "In the RNA-seq data, heg1 and ccm genes were screened as genes related to cardiovascular development in the zebrafish cardiomyopathy embryo heart when treated with NXT." (PMID 34775978, 2021). "qRT-PCR analysis further showed that NXT could restore cardiomyopathy phenotype in zebrafish through HEG1-CCM signaling." (PMID 34775978, 2021). "It was suggested that HEG1-CCM signaling might be one of molecular targets of NXT in the treatment of cardiomyopathy." (PMID 34775978, 2021). "Through TFD-induced zebrafish cardiomyopathy model and the heg1 mutant of the congenital zebrafish cardiomyopathy model, we proved that NXT had a good therapeutic effect on cardiomyopathy, and could restore myocardial injury and cardiac dysfunction." (PMID 34775978, 2021). "Transcriptome and bioinformatics analyses further revealed that NXT could restore cardiomyopathy in zebrafish through HEG1-CCM signaling, which might be one of molecular pathological mechanisms of NXT in the treatment of cardiovascular diseases." (PMID 34775978, 2021). "Moreover, the heg1 mutant of zebrafish congenital cardiomyopathy model was used to further validate the therapeutic effect of NXT on cardiomyopathy." (PMID 34775978, 2021). "Furthermore, by comparing 30 DCM related genes homologous to human in zebrafish hearts based on RNA-Seq data, heg1 was identified as one of the important targets via which NXT could restore cardiomyopathy in zebrafish through HEG1-CCM signaling." (PMID 34775978, 2021). "It indicated that PF and Sal B could significantly recovery cardiomyopathy phenotype, and restore abnormal expression of the vascular markers and myocardial tissue-specific markers, as well as HEG1-CCM signaling." (PMID 34775978, 2021). "However, the abnormal down-expressions of heg1, ccm2, and ccm2l in TFD-induced cardiomyopathy could be restored by NXT treatment confirmed by qRT-PCR validation." (PMID 34775978, 2021).
epithelioid mesothelioma (2 papers, 2024 to 2025). "The emerging marker HEG1 is reportedly 100% specific for epithelioid mesothelioma." (PMID 38409016, 2024).
heart failure (2 papers, 2020 to 2024). Inability of the heart to pump blood at an adequate rate to meet tissue metabolic requirements. "Zebrafish heg1 mutant embryos developed pericardial swelling, pericardial edema, and decreased heart rate, which were similar to the pathophysiology characteristics observed in heart failure patients." (PMID 33198188, 2020). "Zebrafish heg1 mutant demonstrated severe cardiovascular malformations, including atrial ventricular enlargement, heart rate slowing, venous thrombosis and slow blood flow, which were similar to human heart failure and thrombosis phenotype." (PMID 33198188, 2020).
ovarian carcinoma (2 papers, 2009 to 2025). A malignant neoplasm originating from the surface ovarian epithelium. "RT-PCR analyses of ovarian cancer samples validated gene expression profiles of TMEM158, GBE1 and HEG1 from a chromosome 3 transcriptome analysis and IGFBP4, PTRF and C1QTNF1 from a chromosome 17 transcriptome analysis." (PMID 19580657, 2009).
deafness (1 paper, 2021). An inherited or acquired condition characterized by the complete loss of the ability to hear from one or both ears. "HEG1 is involved in cardiovascular development and therefore seemed unlikely to be involved in the development of deafness." (PMID 33805165, 2021).
dilated cardiomyopathy (1 paper, 2020). Cardiomyopathy which is characterized by dilation and contractile dysfunction of the left and right ventricles. "Loss of HEG1 will affect the stabilization of vascular endothelial cell connection and eventually lead to dilated cardiomyopathy (DCM)." (PMID 33198188, 2020).
Hypertension (1 paper, 2021). The presence of chronic increased pressure in the systemic arterial system. "HEG1 was negatively associated with BMI, LDL, and hypertension." (PMID 34706560, 2021).
liver cancer (1 paper, 2025). An epithelial or non-epithelial malignant neoplasm that arises from the liver. "IGF2BP1 arginine methylation mediated by protein arginine methyltransferase 3 (PRMT3) promotes oxaliplatin resistance through stabilizing the mRNA of HEG1 in liver cancer." (PMID 40592832, 2025).